BRCA2 (BRCA2 DNA repair associated)
Diseases named in the same sentence as BRCA2 in open-access papers (continued):
Sharing a sentence is not in itself a finding about the gene and the disease.
ovarian carcinoma (continued). "Germline mutations in the high penetrance genes BRCA1 and BRCA2 are responsible for the vast majority of families containing multiple cases of ovarian cancer (>3 cases) and two or more cases of breast and ovarian cancer." (PMID 19543528, 2009). "Several PARP-1 inhibitors are currently in phase I or II of clinical monotherapy trials in BRCA1/BRCA2-deficient breast or ovarian cancers." (PMID 19319136, 2009). "The precise identification of germline BRCA1 and BRCA2 mutations is a major concern for geneticists counseling families with a high risk of breast and ovarian cancers." (PMID 21637503, 2009). "Breast and ovarian carcinomas in BRCA1 or BRCA2 mutation carriers usually have somatic deletions of the wildtype allele, rendering the neoplasm BRCA1 or BRCA2 deficient." (PMID 19602291, 2009). "BRCA1 and BRCA2 were originally identified based on genetic linkage to families with an increased risk of breast and ovarian cancer." (PMID 20046879, 2009). "Women with BRCA1 or BRCA2 mutation have a substantially increased risk of breast and ovarian cancer compared with the general population." (PMID 18410690, 2008). "Germline inactivating mutations in BRCA1 and BRCA2 underlie a major proportion of the inherited predisposition to breast and ovarian cancer." (PMID 18298804, 2008). "Studies have indicated that the risk of ovarian cancer is greatest in women with BRCA2 mutations localized in nucleotides 3035–6629." (PMID 18597679, 2008). "Women with BRCA1 or BRCA2 mutations have a substantially increased risk of breast and ovarian cancer compared with the general population." (PMID 18410690, 2008). "The BOADICEA model can be used to estimate the likelihood of carrying a BRCA1 or a BRCA2 mutation, and the risks of developing breast or ovarian cancer." (PMID 18349832, 2008). "BRCA1 and BRCA2 mutations account for an important fraction of hereditary breast and ovarian cancer cases." (PMID 18489799, 2008). "One thousand and ten unrelated high-risk probands with breast and/or ovarian cancer were analysed for the presence of a BRCA1 or BRCA2 gene mutation at the Masaryk Memorial Cancer Institute (Czech Republic) during 1999–2006." (PMID 18489799, 2008). "Even this reliance on the presence of ovarian cancer for BRCA2 has been questioned by the report of 58% of BRCA2 related ovarian cancer families having mutations outside the OCCR." (PMID 18513387, 2008). "Since the identification of the BRCA1 and BRCA2 genes a great deal of debate has focussed on the issue of breast and ovarian cancer risk associated with mutations in these genes." (PMID 18513387, 2008). "Germline mutations in BRCA1 and BRCA2 cause an increased lifetime risk for breast and ovarian cancer." (PMID 18501021, 2008). "Although we tested 13 of 74 patients with ovarian cancer for BRCA1 or BRCA2 mutations and found a mutation in 10 of the 13 patients with familial cancer, this result is not representative of the whole population of patients." (PMID 18268495, 2008). "The discovery of the BRCA1 and BRCA2 genes has transformed the management of women who are at high risk of developing breast and ovarian cancer." (PMID 18627636, 2008). "BRCA1 and BRCA2 are the two most frequently mutated genes underlying inherited breast and ovarian cancer." (PMID 18298804, 2008). "BRCA1 and BRCA2 are the two major susceptibility genes, accounting for varying fraction of familial breast and ovarian cancer cases in different populations." (PMID 18501021, 2008). "BRCA1 and BRCA2 are the two most important genes associated with familial breast and ovarian cancer susceptibility." (PMID 18501021, 2008). "We apply our methods to incorporate oophorectomy into the BRCAPRO model, which predicts a woman's risk of carrying mutations in BRCA1 and BRCA2 based on her family history of breast and ovarian cancer." (PMID 17378937, 2007).
ovarian carcinoma (continued). "In summary, here we propose a fast, flexible and cost-effective multiplex assay of the ten most frequent BRCA1 and BRCA2 mutations in Spain, for the initial screening of Spanish and Spanish ancestry population's breast/ovarian cancer families." (PMID 17603881, 2007). "Studies of families with breast and/or ovarian cancer who harbour disease-associated BRCA2 mutations have reported that male family members who carry such mutations have an increased RR of prostate cancer." (PMID 17700570, 2007). "The current study is population-based; patients were not selected on the basis of family history of prostate, breast, or ovarian cancer, which offers a less-biased assessment of the role of BRCA2 protein-truncating mutations in men from the general population." (PMID 17700570, 2007). "BRCA1 and BRCA2 mutations increase breast and ovarian cancer risks substantially enough to warrant risk reduction surgery, despite variable risk estimates." (PMID 17213823, 2007). "BRCA1 and BRCA2 were identified as genes mutated in hereditary breast/ovarian cancer by genetic analysis in families with multiple cases of these malignancies." (PMID 17213823, 2007). "A Finnish study of 107 breast or ovarian cancer families reported a five-fold increase in the RR of prostate cancer among men carrying protein-truncating BRCA2 mutations (RR=4.9, 95%CI 1.8–11.0)." (PMID 17700570, 2007). "BRCA1 and BRCA2 are critical to prevent breast and ovarian cancers in mutation carriers but the proteins participate in processes that are fundamental for survival in other types of cells." (PMID 17683622, 2007). "A smaller Dutch study, based on 199 malignancies other than breast or ovarian cancer, estimated pancreatic cancer risk in BRCA2 carriers by age 70 years at 4.1% (95% CI 1.0–7.3%) in men and 1.4% (95% CI 0–3.4%) in women." (PMID 17213823, 2007). "Women carrying a germline heterozygous mutation in either BRCA1 or BRCA2 are predisposed to breast and ovarian cancer." (PMID 17324252, 2007). "Mutations in BRCA1 gene (and BRCA2) are associated with inherited breast and ovarian cancer, although the exact nature of this tissue specificity is incompletely understood." (PMID 17850658, 2007). "Based on these calculations the probability of finding one ovarian cancer in the BRCA-1 mutation carrier group was 92% and the probability of finding one ovarian cancer in the BRCA-2 mutation carrier group was 8.7%." (PMID 16495917, 2006). "The 3398delAAAAG mutation in BRCA2 was recently found to recur in breast and/or ovarian cancer families from the French Canadian population of Quebec, a population that has genetic attributes consistent with a founder effect." (PMID 16539696, 2006). "BRCA1 and BRCA2 mutation carriers are at increased risk for developing both breast and ovarian cancer." (PMID 16563180, 2006). "A number of models that predict BRCA1 and BRCA2 mutation carrier risks and/or breast and ovarian cancer risks have been reported in the literature." (PMID 16417652, 2006). "Founder mutations in both BRCA1 and BRCA2 genes have been characterized in French-Canadian high-risk breast/ovarian cancer families." (PMID 16417652, 2006). "It is estimated that 5% to 10% of cancer is caused by autosomal dominant inherited genetic changes, such as BRCA1 and BRCA2 mutations in breast and ovarian cancer." (PMID 15888219, 2005). "The complex also interacts directly with the FANCD1 protein), now known to be the product of the breast and ovarian cancer predisposition gene, BRCA2." (PMID 15860134, 2005). "Women identified as carriers of a mutation in one of the breast and ovarian cancer-susceptibility genes BRCA1 or BRCA2 have strongly elevated risks of developing breast or ovarian cancer." (PMID 16052221, 2005). "Germline mutations in the BRCA1 and BRCA2 genes have been shown to account for the majority of hereditary breast and ovarian cancers." (PMID 16168118, 2005).
ovarian carcinoma (continued). "The BRCA2 exon 3 542G>T mutation was present in nine family members, among whom five women were diagnosed with BC and one was diagnosed with ovarian cancer." (PMID 14735197, 2004). "The contribution of BRCA2 mutations to ovarian cancer is predicted to be highest at age 50 years (1.6%)." (PMID 15381934, 2004). "Mutations in the 5′-end of BRCA1 and BRCA2 were associated with a significantly increased risk for ovarian cancer relative to the central portion of the gene." (PMID 15026808, 2004). "Women with a BRCA1 or BRCA2 germline mutation are at an increased risk of developing breast and ovarian cancer." (PMID 15083174, 2004). "The predicted prevalences of BRCA1 and BRCA2 mutations among unselected cases of breast and ovarian cancer are also consistent with observations from population-based studies." (PMID 15381934, 2004). "Germ line mutations in the BRCA1 and BRCA2 genes predispose individuals to breast and ovarian cancer." (PMID 15353005, 2004). "In conclusion, we found reduced ovarian cancer risk associated with long-term oral contraceptive use among carriers of BRCA1 or BRCA2 mutations." (PMID 15545966, 2004). "Since the efficiency of these screenings methods is still not clear, prophylactic surgery of the ovaries for patients with proven BRCA1 or BRCA2 mutations or a strong family history of breast and/or ovarian cancer is an important option." (PMID 15083174, 2004). "For the other family with two mutations (BRCA1 and BRCA2), it has been possible to identify the separate routes of inheritance and hence to calculate the numbers of breast and ovarian cancers attributable to each mutation." (PMID 12698193, 2003). "In assessing the numbers of breast and ovarian cancers recorded in mutation-positive families, two families have been excluded (both with BRCA2 mutations)." (PMID 12698193, 2003). "Mutations within the 5′ two-thirds of BRCA1 carry a significantly higher relative risk of ovarian cancer and the same is true for mutations within the central portion of BRCA2 (the ‘OCCR’)." (PMID 12698193, 2003). "Using Fishers exact test we observed a significant difference between the incidence of BRCA2 mutations in the breast/male stomach cancer families compared to the breast/ovarian cancer families (P<0.025)." (PMID 12373604, 2002). "This is rarely assessed despite the fact that if women have a BRCA1 or BRCA2 mutation they are at a greatly increased lifetime risk of developing ovarian cancer." (PMID 11857010, 2002). "Women who have inherited a mutation in the BRCA1 or BRCA2 gene have approximately an 80% risk of developing breast cancer over their lifetime, particularly at a young age, and a 40–60% lifetime risk of ovarian cancer." (PMID 11857010, 2002). "We have analysed 81 families with a history of breast and/or ovarian cancer for the presence of germline mutations in BRCA2 with a number of different mutation screening techniques." (PMID 10638982, 2000). "Unique germline mutations in BRCA1 and BRCA2 account for inherited predisposition to breast and ovarian cancer in high-risk families." (PMID 9667663, 1998). "Truncating mutations in BRCA2 on chromosome 13q also predispose to ovarian cancer, although they confer a lower risk than mutations in BRCA1." (PMID 9579822, 1998). "Previously published data indicate that the risks of breast and ovarian cancer conferred by BRCA2-truncating mutations varies with the position of the mutation in the gene." (PMID 9579822, 1998). "Loss of heterozygosity detected using chromosome 13q markers in the vicinity of BRCA2 is observed in most cancers arising in carriers of germline BRCA2 mutations and also in 30-50% of sporadic breast and ovarian cancers." (PMID 9365162, 1997).
ovarian carcinoma (continued). "Additionally, the increased presence of BRCA2 variants in ovarian cancer from the cancer-specific analysis showed trending significance in the traditional PheWAS (phecode 184.11, “malignant neoplasm of ovary”, p = 1.6 × 10−3, OR = 32)." (PMID 39799398, 2025). "Some well-established nLTR-derived examples include de novo Alu insertions into BRCA1 and BRCA2, which predispose carriers to hereditary breast and ovarian cancers, and germline L1 insertions into the APC TSG, which underlie familial adenomatous polyposis and increase colorectal cancer risk." (PMID 40950107, 2025). "Pathogenic variants in BRCA1 and BRCA2 and several other genes are risk factors for ovarian cancer, conferring a 17–44% lifetime risk of ovarian cancer for females with pathogenic variants in the BRCA1 or BRCA2 genes, as well as increased risks for breast (72%) and other cancers." (PMID 40227675, 2025). "BRCA1 and BRCA2 are tumor suppressor genes located on chromosomes 17q21 and 13q12, respectively, which are responsible for an increased risk of developing breast and ovarian cancer." (PMID 40429755, 2025). "Germline pathogenic variants in BRCA1 and BRCA2 confer high risks of breast and ovarian cancer." (PMID 40399999, 2025). "Additionally, this finding agrees with the original data reported in TCGA whereby the majority (55%) of pathogenic BRCA2 variants occurred in patients with breast or ovarian cancer." (PMID 39799398, 2025). "Mutations in BRCA1 and BRCA2 genes are the leading cause of hereditary breast and ovarian cancer." (PMID 40543584, 2025). "BRCA1 and/or BRCA2 mutations (BRCAm) are established mechanisms of homologous recombination deficiencies (HRDs) known to play a role in ovarian cancer and may be germline (g) or somatic (s) in origin." (PMID 40097725, 2025). "Additionally, genetic mutations, particularly in the BRCA1 and BRCA2 genes, significantly increase the risk of ovarian cancer." (PMID 40896438, 2025). "BRCA2 variants were identified in 12.86% of patients, with a higher prevalence in ovarian cancer." (PMID 41283249, 2025). "In humans, mutations in BRCA1 and BRCA2 predispose individuals to breast and ovarian cancer." (PMID 40852952, 2025). "Approximately 10–15% of women with epithelial ovarian cancer carry a BRCA1 or BRCA2 mutation." (PMID 41219748, 2025). "In our work, we aimed to identify proteins specifically upregulated in mutated BRCA1 and BRCA2 breast and ovarian cancers that could be used as targets for the development of novel therapies." (PMID 40647506, 2025). "Similarly, in the PRIMA trial, niraparib significantly improved survival outcomes in patients with homologous recombination deficiency (HRD), including those with BRCA1 or BRCA2 mutations, in newly diagnosed advanced ovarian cancer at high risk of recurrence." (PMID 40075604, 2025). "Therefore, we characterised the ID8 model of ovarian cancer, with matched cell lines with specific mutations in Brca1 and Brca2." (PMID 40977519, 2025). "Since both parents of the proband were healthy at the age of 73 and given the high prevalence of pathogenic variants in the BRCA1 and BRCA2 genes in ovarian cancer, as well as their significant therapeutic implications, the initial molecular analysis focused on these two genes." (PMID 40076915, 2025).
ovarian carcinoma (continued). "However, half of the identified pathogenic HDR gene variants in EC patients were in BRCA1 or BRCA2, which calls for counseling in regard of breast and ovarian cancer risk in some 2% of EC patients and their family members from Kazakhstan." (PMID 39400928, 2025). "Decades of research have shown that mutations in BRCA1, BRCA2, and other genes involved in homologous recombination (HR) are significant prognostic indicators for survival and response to platinum-based therapy in ovarian cancer." (PMID 40076854, 2025). "BRCA1 and BRCA2 mutations associated with breast and ovarian cancers." (PMID 41180630, 2025). "Approximately 14% of ovarian cancer cases are a result of mutations in BRCA1 or BRCA2 genes." (PMID 40894326, 2025). "Finally, PEO1 and PEO4 are ovarian cancer lines derived from the same patient, which respectively carry inactivating and rescuing BRCA2 mutations." (PMID 39805921, 2025). "BRCA1 and BRCA2 mutations were identified as ovarian cancer risk factors." (PMID 40869932, 2025). "Similarly, for ovarian cancer (OC), the risk of development in healthy individuals is estimated to be 1–2%, while in BRCA2-positive individuals, it increases to 39–44%, with a greater impact for BRCA1 variants (11–17%)." (PMID 38792636, 2024). "Moreover, a study in 2022 that included 250 women with BC and 240 with ovarian cancer undergoing germline molecular testing showed c.9371A>T to be one of the most common variants identified for BRCA2." (PMID 39796670, 2024). "Additionally, mutations in BRCA1 and BRCA2 are linked to heightened risks of breast and ovarian cancers." (PMID 39391434, 2024). "BRCA1 and BRCA2 stand out as widely recognized genetic susceptibility genes for ovarian cancer." (PMID 38461424, 2024). "In fact, the most prominent disparity observed between the risks observed in carriers with diverse ethnic backgrounds and those identified in individuals of Ashkenazi Jewish descent pertains to the heightened ovarian cancer risk associated with BRCA2 pathogenic variants in AJ populations." (PMID 38397209, 2024). "The apparent smaller effect on mortality in carriers of BRCA2 PGVs compared to BRCA1 PGVs may be due to the lower risk of ovarian cancer in carriers of BRCA2 PGVs as well as the more aggressive biological characteristics of BRCA1-associated BC." (PMID 38672070, 2024). "Furthermore, the involvement of the homologous recombination DNA repair pathway, which is frequently affected by BRCA1 and BRCA2 mutations, further underscores the link between these genetic alterations and the development of ovarian cancer." (PMID 38543119, 2024). "Furthermore, 10% to 21% of women with BRCA1 mutations will present with ovarian cancer by age 50 years compared with only 3% to 5% of women with BRCA2 mutations." (PMID 39028933, 2024). "Germline mutations in BRCA1 and BRCA2 genes are among the main causes of hereditary ovarian cancer." (PMID 38641594, 2024). "In October 2019, the Ministry of Food and Drug Safety of Korea approved olaparib as a first-line maintenance treatment for patients newly diagnosed with advanced, platinum-sensitive epithelial ovarian cancer with BRCA1 or BRCA2 pathogenic or likely pathogenic variants." (PMID 39590126, 2024). "The BRCA1 and BRCA2 genes were discovered via research on breast–ovarian cancer predisposition." (PMID 38612902, 2024). "Therefore, the study aimed to investigate the prevalence of germline mutations in BRCA1 and BRCA2 in women with ovarian cancer treated in the Public Health System in Pernambuco, Brazil." (PMID 38641594, 2024). "The mutations in BRCA1 and BRCA2 increase the risk of developing breast and ovarian cancers." (PMID 39456709, 2024). "Both BRCA2 variants have been previously detected with low frequency rates (0.82% and 1.03%, respectively) in women of the same population affected by breast and/or ovarian cancer." (PMID 38974244, 2024). "Clinically, BRCA1- and BRCA2-mutated ovarian cancers have been treated as the same disease." (PMID 38017453, 2023).